LEP (leptin)
Diseases named in the same sentence as LEP in open-access papers (continued):
Sharing a sentence is not in itself a finding about the gene and the disease.
Obesity (continued). "Leptin sends a signal to the hypothalamus to inhibit appetite; in obesity, a leptin resistance state has been found and the serum levels are increased." (PMID 27527189, 2016). "Previous studies provide evidence that adipokine leptin increases production of catabolic and proinflammatory factors in chondrocytes and serves as a link between obesity and osteoarthritis (OA)." (PMID 27716333, 2016). "Tomato and broccoli treatment also improved the lipid profile, the API, as well as adiponectin and leptin levels in HFD-induced obesity rats of this study." (PMID 27430475, 2016). "The current study aimed to investigate the potential relationship between leptin and adiponectin, and obesity, blood lipids and insulin resistance in the Cameroonian population." (PMID 27189377, 2016). "It is possible that, in obesity and T2DM, a deficiency in leptin uptake and binding is present due to high levels of triglycerides then suppressing leptin action." (PMID 27147943, 2016). "Although the evidence regarding the effect of leptin on inflammatory response is controversial, we have confirmed our findings in other models of obesity such as db/db and melanocortin 4 receptor knock out mice." (PMID 27500833, 2016). "It is reported that PTP1B also involved in the leptin signaling, PTP1B-deficient mice are resistant to high-fat diet induced obesity." (PMID 26808535, 2016). "These responses make leptin a promising biological target for a complementary therapy to the traditional insulin treatments for diabetes and obesity." (PMID 27055280, 2016). "Namely, disorders in leptin production or action result, beyond severe early-onset obesity, in altered immune function due to T-cell defects and pubertal delay, the latter being in conflict with the premature pubertal development and menarche of our patient." (PMID 26956990, 2016). "Apart from its role in obesity, recent studies have drawn attention to the role of leptin in the pathogenesis of T2DM and insulin resistance." (PMID 27195302, 2016). "Moreover, augmented leptin levels could also trigger the production of pro-inflammatory t-helper 1-type cytokines and contribute to the inflammatory response associated with the obesity." (PMID 27845741, 2016). "Many factors, such as insulin/leptin dysregulation and inflammation, mediate the effect of obesity and cognition and motor behaviors." (PMID 26881095, 2016). "In obesity and type 2 diabetes, circulating levels of leptin and adiponectin are differentially regulated (up- and downregulated, respectively)." (PMID 27708616, 2016). "The findings on the modulatory effect of Eui-E-In-Tang on serum level of leptin deserve to be studied further to make a safe and effective treatment for obesity." (PMID 27630731, 2016). "Leptin is one of the highly studied molecules in obesity after insulin (present in7.4% of total abstracts)." (PMID 26886906, 2016). "Both leptin and insulin biomarkers are used as predictors of weight gain and obesity during infancy." (PMID 27440187, 2016). "Levels of the adipocyte-derived hormone, leptin, which strongly correlate with obesity and diabetes, were initially normal in PLB4 mice, but were drastically elevated at 4 and 8 months when adiposity was increased." (PMID 27138913, 2016). "To assess this, we studied ATCM from the JCR:LA-cp rat which exhibits obesity and concomitant leptin resistance and compared the results to lean, metabolically normal controls." (PMID 26731409, 2016). "Taken together, these data support targeting nesfatin-1 signaling as a leptin-independent strategy for treating obesity." (PMID 28105016, 2016). "Sex‐specific associations of serum leptin and C‐reactive protein (CRP) with cancer death in the NHANES III, stratified by obesity status." (PMID 26632325, 2016). "Others have used genetic (leptin or leptin receptor defective) and dietary models to show that obesity enhances DEN-induced hepatocarcinogenesis." (PMID 30873458, 2016).
Obesity (continued). "It would be interesting to evaluate if maternal leptin values represent a predictor for infant obesity." (PMID 27338468, 2016). "Sub-cellular network analysis demonstrated the shared biological significance underlying three canonical signaling pathways: insulin receptor, leptin signaling in obesity, and T2D." (PMID 27623749, 2016). "Our findings suggest that although PUMA is dispensable for glucose homeostasis in lean and obese mice, it can affect leptin levels and food intake during obesity." (PMID 27033313, 2016). "There are also studies suggesting a gene-gene interaction between the LEP and LEPR variants in a genetic susceptibility to the development of obesity." (PMID 27240401, 2016). "Both, insulin and leptin have been considered the key players linking obesity, autonomic derangement, and sympathetically mediated diseases (e.g. hypertension)." (PMID 26781642, 2016). "The shared phenotypes of aripiprazole and mice with impaired LEP/LEPR function like “obesity”, “insulin resistance” and “glucose tolerance impaired” point to alterations of leptinergic signalling by the antipsychotic aripiprazole." (PMID 27673331, 2016). "SOCS-3 is a leptin-inducible inhibitor of leptin signalling and a potential mediator of leptin resistance in obesity." (PMID 27479001, 2016). "Leptin treatment is considered to be ineffective in the general population of patients with obesity and/or type 2 diabetes due to development of leptin resistance, hyperleptinemia, and insulin resistance." (PMID 27055280, 2016). "Rare homozygous loss-of-function mutations in the leptin-encoding gene (LEP) causeleptin deficiency that leads to hyperphagia and severe obesity, which can be correctedby exogenous leptin administration." (PMID 26833098, 2016). "In the present study, we investigate the changes of serum kisspeptin and leptin levels in children and adolescents from Northern China in different pubertal stages (T1–T5) and normal/overweight/obesity status." (PMID 27990162, 2016). "Previous studies have suggested that people with obesity showed elevated serum levels of leptin as well as lipid dysfunction and proprotein convertase subtilisin/kexin type 9 (PCSK9) played an important role in the regulation of lipid metabolism recently." (PMID 27663646, 2016). "For example, leptin, an adipokine whose levels are increased in obesity, has a direct role regulating the gut microbiota composition, through the modulation of antimicrobial peptides secretion by Paneth cells in the gut." (PMID 27043550, 2016). "We investigated the alleviation effect of KBH-1 and its possible molecular mechanism in obesity-induced hepatic steatosis and leptin resistance in the hypothalamus." (PMID 27618865, 2016). "The neuroendocrine effects of leptin on metabolism hold promise to be translated into a complementary therapy to traditional insulin therapy for diabetes and obesity." (PMID 27055280, 2016). "We also tested leptin sensitivity in young LRbCre/Bbs1fl/fl mice before the development of obesity and hyperleptinemia." (PMID 26926121, 2016). "One way of seeing the effects of diet-related factors on obesity is evaluating leptin levels in the blood." (PMID 26869995, 2016). "Although leptin has been considered a candidate for combating obesity, leptin insensitivity represents the barrier to its proper function in obese subjects." (PMID 27812350, 2016). "Leptin’s main anti-obesity signaling pathway is predominantly involved in its binding to the Ob-Rb long isoform of the leptin receptor." (PMID 27677243, 2016). "Obesity causes an abnormal expression of adipokines (e.g., tumor necrosis factor-α [TNF-α], interleukin-6 [IL-6], adiponectin, leptin), which leads to a proinflammatory status." (PMID 27964760, 2016). "A link to diabetes can also be found for “Leptin Signaling in Obesity”, as leptin is involved in the regulation of obesity, which in turn is an important risk factor for T2D." (PMID 27019061, 2016).
Obesity (continued). "High concentrations of leptin in obesity are indicative of a state of leptin resistance implicating impaired receptor sensitivity and action." (PMID 28050279, 2016). "The mean maternal leptin concentrations were significantly higher in women with obesity class III compared to women in obesity class I, at all times when plasma leptin were measured." (PMID 27257506, 2016). "We further show that loss of BBSome subunits, but not IFT88, impairs the trafficking of the LRb to the plasma membrane leading to leptin resistance independently of cilia and obesity." (PMID 26926121, 2016). "Leptin resistance is a very common characteristic of obesity, and its serum levels are higher in obese humans when compared to healthy subjects." (PMID 26869995, 2016). "First, in HFD-induced obesity rats, we assessed the serum leptin level and the feed efficiency ratio." (PMID 27618865, 2016). "Exogenous leptin administration failed as an effective approach to manage obesity, even though therapies that improve leptin sensitivity have become one of the developing alternative approaches to treat obesity and related comorbidities." (PMID 27534844, 2016). "Recent studies have shown that the level of circulating leptin is elevated in obese patients and have suggested a relationship between obesity and postoperative lymphedema." (PMID 27366905, 2016). "In the present study, the results demonstrated that an obesity-related environment, as simulated by leptin stimulation or adipocyte-conditioned medium incubation, promotes 4T1 breast cancer cell proliferation." (PMID 27983683, 2016). "Obesity can affect brain structure, leptin/insulin dysregulation, oxidative stress, cerebrovascular function, blood-brain barrier, and inflammation, which are involved in the deterioration of cognitive and motor functions." (PMID 26881095, 2016). "Particularly the effect of the acute stress on leptin has important implications for the role of short-term stress in the etiology of obesity, and dysfunctional reactions to stress in obese individuals." (PMID 27020850, 2016). "Serum leptin levels correlates with obesity and hepatic steatosis and the leptin receptor in liver regulates lipid droplet accumulation in the liver." (PMID 27902747, 2016). "Next, we assessed the potential correlation with markers for obesity: BMI, waist circumference, and leptin concentration." (PMID 27443391, 2016). "After sacrifice, biochemical markers of obesity and insulin resistance including oral glucose tolerance test, adiponectin, leptin, and retinol binding protein-4 (RBP4) were measured." (PMID 26842399, 2016). "In this study, the major goal was to determine if human leptin played a role in regulating the uptake of LDL by PCSK9 in hepG2 cells for the sake of exploring the potential links of leptin with PCSK9 in obesity." (PMID 27663646, 2016). "In humans, the concentration of circulating leptin is altered by obesity and the promoter methylation of leptin is also altered in obese individuals." (PMID 26789724, 2016). "In summary, our results demonstrated that ASI prevented the process of obesity, lowered lipid contents, and enhanced fat oxidation in obese mice by interfering thermogenic network and ameliorating leptin resistance." (PMID 27444146, 2016). "Leptin, an anti-obesity hormone secreted from adipocytes, plays critical roles in the regulation of appetite and feeding-related behavior." (PMID 27677243, 2016). "To assess the effect of miR-30c on the arterial thrombosis relevant to DM2, we fed mice a HFD for 14 weeks, which produced obesity and hyperglycaemia, and high plasma leptin levels." (PMID 27819307, 2016). "Taken together, our results reveal new links between obesity and cartilage damage that are induced by leptin-mediated effects on cell behaviour and senescence." (PMID 27077804, 2016).
Obesity (continued). "Upon observation of increased body weight and obesity-related factors, the current study dissected the leptin/IGF1 signaling axis previously unexplored in relation to heavy ion space radiation in mouse intestine and colon." (PMID 27558773, 2016). "In this study, the SD group showed features consistent with obesity development, i.e., significant increase in body weight, fat mass, adipose tissue inflammation, and serum total cholesterol, cLDL, leptin and insulin concentrations." (PMID 27656148, 2016). "Taken together, our results suggest new links between obesity and cartilage damage that involve leptin-mediated effects on CPCs differentiation and senescence." (PMID 27077804, 2016). "Mutations of the leptin, leptin receptor, POMC, and MC4-R genes lead to severe obesity in rodents and in humans, underscoring the importance of central leptin-melanocortin signaling for the regulation of energy balance." (PMID 27609221, 2016). "Deletion of SOCS3 in hypothalamic neurons enhances leptin sensitivity, reduces appetite, and protects from diet-induced obesity; while overexpression of SOCS3 in proopiomelanocortin (POMC) neurons leads to hyperphagia and obesity." (PMID 27812350, 2016). "Although mechanistic links between stress, eating behavior, and obesity are not fully understood, leptin has been repeatedly suggested as an important biomarker in the relationship between stress and weight gain." (PMID 26872268, 2016). "The sympatho-excitatory actions of leptin to the kidney makes an important contribution to the abnormally elevated RSNA observed in obesity or overweight conditions." (PMID 28119622, 2016). "While whole body insulin sensitivity was not different between WT and GPRKO mice, WT female mice fed a HFD had higher insulin and leptin levels than those in GPRKO female mice (p < 0.05), which are typically associated with obesity and insulin resistance." (PMID 27698362, 2016). "The anorexigenic hormone, leptin, and the orexigenic hormone, ghrelin, are two hormones that have been recognized to have a major influence on energy balance and obesity." (PMID 27699065, 2016). "The main symptom of NAFLD is the accumulation of triglycerides (TG) and accompanying steatosis and obesity through leptin resistance as the pathological status in clinics." (PMID 27618865, 2016). "Alterations in the levels of adipokines including a decrease in adiponectin and increases in leptin and IL‐6 are primary links between obesity and systemic inflammation, as well as signs of progression of metabolic dysfunction." (PMID 26990883, 2016). "In vivo, all of these mechanisms are likely to contribute to the quantity of leptin-evoked effects, obesity seemingly favoring enhanced responses in many ways." (PMID 27716333, 2016). "Previous studies demonstrated that ER stress was enhanced in a mouse model of obesity and was suggested to be involved in the development of leptin resistance." (PMID 27375555, 2016). "Hypothalamic HDAC5 overexpression improves leptin action and partially protects against HFD-induced leptin resistance and obesity." (PMID 26923837, 2016). "In conclusion, this study provides evidence that GBR ameliorates obesity by suppressing body weight gain and food intake while improving lipid profiles and reducing leptin level and white adipose tissue mass in obese rats fed on HFD." (PMID 27216718, 2016). "Insulin and leptin resistance are seen as the interface between inflammation and metabolism in obesity-related CVD." (PMID 27598982, 2016). "Taken together, these data indicate that the leptin resistance observed in male C2αD1268A/WT mice is accompanied by age-dependent obesity, with an increase in adipose tissue and enhanced hepatic lipid accumulation." (PMID 27138914, 2016). "We showed that a sub-physiological concentration of leptin produced by these engrafts can effectively improve glucose tolerance in mice with genetic and diet-induced obesity." (PMID 27055280, 2016).
Obesity (continued). "Chronic inflammatory state in obesity is maintained by interactions between leptin and inflammation, where an increase on pro-inflammatory cytokines leads to leptin release." (PMID 26862350, 2016). "The effects of E2 and selective agonists of ER subtypes on leptin-related intracellular signaling pathways were investigated to understand potential mechanisms of estrogenic protection in leptin-induced HepG2 cell growth and thus obesity-related HCC." (PMID 26982332, 2016). "Genetic variability in the LEP and LEPR gene was previously associated with susceptibility to obesity and obesity-related metabolic diseases." (PMID 28051281, 2016). "Leptin is another adipokine involved in the pathogenesis of obesity, insulin resistance, inflammation, and diabetes." (PMID 27200209, 2016). "We fed ThrbPV/PVPten+/−mice a high fat diet (HFD) to induce obesity marked by increased body weight, enlarged fat cells, and elevated serum leptin levels." (PMID 27145454, 2016). "We then examined if some of the characteristic features of serum in obesity (high leptin, high insulin, and high free-fatty acids) affect leptin responsiveness." (PMID 26849804, 2016). "The hypothalamus produces a number of hormones and neuropeptides and is enriched with receptors for non-brain derived hormones like insulin and adipose tissue-derived adipokines like leptin that are related to obesity." (PMID 27845741, 2016). "Leptin is a 16 kDa adipocyte-derived hormone that is secreted in proportion to the adipose stores, with high circulating plasma levels in obesity resulting in leptin resistance, which boosts tau phosphorylation, in turn increasing Alzheimer pathology." (PMID 27547756, 2016). "In contrast to our findings, however, a recent report has argued that leptin resistance in BBS mice is secondary to obesity." (PMID 26926121, 2016). "Increased placental leptin gene expression in normal weight women with GDM was reversed when GDM was accompanied by obesity." (PMID 26513002, 2016). "The monogenic determinism of obesity is rarely seen and it is characterised by the deficit of leptin, pro-opiomelanocrotin and leptin receptors." (PMID 27928443, 2016). "Congenital leptin deficiency is a rare form of monogenic obesity and was first reported in two cousins of Pakistani origin with severe early onset obesity who had very low serum leptin levels." (PMID 27075752, 2016). "Consistently, leptin-deficient mice develop severe obesity, whereas SOCS-3 conditional knockout mice are resistant to diet-induced obesity." (PMID 27716333, 2016). "The serum level of adiponectin, in contrast to leptin, is reduced in the state of obesity, insulin resistance and diabetes mellitus and its reduction plays a significant role in their development." (PMID 27983705, 2016). "In contrast to anorexia, obesity typically results in increased leptin levels which, in turn, should suppress MAT." (PMID 27579023, 2016). "Our findings show a distinct aspect of obesity-induced adipocyte remodelling exemplified by reduced adiponectin and enhanced leptin secretion." (PMID 26731409, 2016). "Obesity and a HFD, even after 3 days, are associated with systemic low-grade inflammation and leptin resistance on the molecular signaling level." (PMID 27551276, 2016). "With respect to obesity, leptin and inflammation have gained increasing interest with regards to their potential implications in cancer development." (PMID 26632325, 2016). "Deletion of SF-1 in the VMH resulted in dysregulated insulin and leptin homeostasis and late onset obesity due to increased food intake under normal chow and high fat diet conditions." (PMID 27598259, 2016). "Obesity is further characterized by decreased energy expenditure, and heightened food intake, while high levels of leptin are released." (PMID 27147943, 2016).